JMJD8 (jumonji domain containing 8)
Description:
Functions as a positive regulator of TNF-induced NF-kappa-B signaling. Regulates angiogenesis and cellular metabolism through interaction with PKM.
Synonyms: C16orf20; PP14397
Tractability: Antibody: UniProt predicts a signal peptide or a membrane-spanning region. PROTAC: its protein half-life has been measured.
Gene: Protein-coding gene on chromosome 16 (681,666 to 684,528, reverse strand). Ensembl gene ENSG00000161999.
Subcellular location: Endoplasmic reticulum lumen; Cytoplasm
Gene Ontology:
Molecular function: protein binding
Biological process: positive regulation of canonical NF-kappaB signal transduction; positive regulation of sprouting angiogenesis; regulation of glycolytic process; regulation of pyruvate kinase activity
Cellular component: cytoplasm; endoplasmic reticulum; endoplasmic reticulum lumen; nucleus
Genetic constraint (gnomAD): Loss-of-function variants: 56 observed, 34.31 expected, observed/expected ratio (o/e) 1.63, 90% interval 1.31 to 1.93. The synonymous counts are far from expectation, so gnomAD's model fits this gene poorly and the ratio says little. Missense variants: 542 observed, 337.93 expected, observed/expected ratio (o/e) 1.6, 90% interval 1.49 to 1.72. Synonymous variants: 261 observed, 155.34 expected, observed/expected ratio (o/e) 1.68, 90% interval 1.52 to 1.86.
Homologues: Orthologues: chimpanzee JMJD8 (99% identical), macaque JMJD8 (98% identical), pig JMJD8 (86% identical), dog JMJD8 (85% identical), rat Jmjd8 (83% identical), mouse Jmjd8 (82% identical), guinea pig JMJD8 (80% identical), tropical clawed frog jmjd8 (72% identical), zebrafish JMJD8 (56% identical), Caenorhabditis elegans C27F2.9 (46% identical), Drosophila melanogaster CG14331 (12% identical). Paralogues in human: JMJD6 (25% identical), JMJD4 (25% identical).
Diseases named in the same sentence as JMJD8 in open-access papers:
JMJD8 is named in the same sentence as 18 diseases in open-access papers, as found by Europe PMC text mining. Sharing a sentence is not in itself a finding about the gene and the disease. The quoted sentences say what the papers report.
colorectal cancer (4 papers, 2019 to 2024). A primary or metastatic malignant neoplasm that affects the colon or rectum. "Another study also showed that miR-873-5p suppresses EMT and colorectal cancer cell proliferation via directly targeting JMJD8 through the NF-κB pathway." (PMID 37382594, 2023). "Besides being a well-known m6A writer, ALKBH5 also collaborates with METTL14/IGF2BPs to suppress tumor cell glycolysis by negatively regulating the JMJD8/PKM2 signaling axis, thereby slowing down colorectal cancer progression." (PMID 38856795, 2024). "Molecular investigations indicate that ALKBH5 collaborates with METTL14/IGF2BPs to suppress tumor cell glycolysis by negatively regulating the Jumonji domain-containing protein 8 (JMJD8)/pyruvate kinase M2 (PKM2) signaling axis, slowing down colorectal cancer progression." (PMID 38856795, 2024).
glioma (2 papers, 2022 to 2023). A benign or malignant brain and spinal cord tumor that arises from glial cells (astrocytes, oligodendrocytes, ependymal cells). "Also, we previously discovered JMJD8 as a risk factor for many cancers, including glioma, and it is consistent with the discoveries in this study." (PMID 36494582, 2023). "In our study, we discovered that JMJD8 reduced TMB, MSI, and HRD possibly via MMR and HRR systems in some cancers like BRCA, and the two repair systems facilitated the stemness maintenance in glioma, HNSC, and OV." (PMID 35898493, 2022).
breast carcinoma (1 paper, 2025). "In this study, we utilized data from The Cancer Genome Atlas (TCGA) to assess the association between JMJD8 expression and clinical characteristics in breast cancer (BRCA) patients through the Wilcoxon signed-rank test and logistic regression." (PMID 40761260, 2025). "The association of JMJD8 with key clinical features underscores its relevance in understanding breast cancer pathology and could inform future therapeutic strategies aimed at targeting this molecule." (PMID 40761260, 2025). "This highlights the potential role of JMJD8 in modulating the immune landscape of breast cancer, warranting further investigation into its implications for immune response and therapeutic strategies." (PMID 40761260, 2025). "The elevated expression of JMJD8 in breast cancer tissues is indicative of its involvement in the progression of the disease and its association with immune cell infiltration patterns." (PMID 40761260, 2025). "Subsequently, in breast cancer animal models, JMJD8 knockdown significantly inhibited the proliferation of breast cancer cells, resulting in reduced tumor size and weight, along with an upregulation of IFN-β." (PMID 40761260, 2025). "This suggests that JMJD8 plays a crucial role in the immune response and tumor progression in breast cancer." (PMID 40761260, 2025). "Our results indicate that JMJD8 is significantly upregulated in breast cancer tissues characterized by advanced pathological stages and higher histological grades." (PMID 40761260, 2025). "This upregulation suggests a potential role for JMJD8 in the pathogenesis of breast cancer and highlights its importance as a candidate for further investigation in this context." (PMID 40761260, 2025). "We investigate the relationship between JMJD8 and the prognosis and immune infiltration microenvironment of breast cancer, exploring its potential as a prognostic biomarker for this type of cancer." (PMID 40761260, 2025). "Our findings revealed that JMJD8 was significantly upregulated in breast cancer tissues when compared to normal adjacent tissues." (PMID 40761260, 2025). "Research has shown that JMJD8 is associated with cGAS-STING pathway and plays a role in various tumor microenvironments, but its relationship with breast cancer remains unclear." (PMID 40761260, 2025). "Our findings support the hypothesis that JMJD8 could serve as a prognostic biomarker, reflecting the immunosuppressive characteristics of the tumor microenvironment and aiding in the development of targeted therapeutic strategies for breast cancer management." (PMID 40761260, 2025). "To further investigate the relationship between JMJD8 and the progression of BRCA as well as immune responses, we established JMJD8 knockout breast cancer cell lines for both cellular and animal studies." (PMID 40761260, 2025).
diffuse large B-cell lymphoma (1 paper, 2022). "To seek whether JMJD8 gene is altered at the genome level, we displayed the JMJD8 pan-cancer CNV and SNV analysis results and found high JMJD8 amplification in BRCA and high deep deletion rates in diffuse large B-cell lymphoma and UCS (>3%), while no high SNV rates were observed." (PMID 35898493, 2022).
lung adenocarcinoma (1 paper, 2021). A carcinoma that arises from the lung and is characterized by the presence of malignant glandular epithelial cells. "Based on the GEPIA database, JMJD8 was negatively associated with overall survival and disease-free survival of lung adenocarcinoma and squamous cell carcinoma." (PMID 33442397, 2021). "Immunohistochemical analysis showed that the expression of JMJD8 in lung adenocarcinoma has statistically significant; and thus, we selected A549 lung adenocarcinoma and H1299 (moderate JMJD8 expression) cells to perform subsequent experiments." (PMID 33442397, 2021).
lung carcinoma (1 paper, 2021). "To evaluate the underlying functions and mechanisms of JMJD8 in non-small-cell lung cancer (NSCLC), in this study, we analyzed the role of JMJD8 in promoting proliferation and invasion of lung cancer cells, as well as its relationship with the EGFR pathway." (PMID 33442397, 2021). "Upon JMJD8 knockdown in lung cancer cell lines, cyclin B1, RhoA, RhoC, MMP9, and N-cadherin were down-regulated, and p21 and E-cadherin were conversely up-regulated." (PMID 33442397, 2021). "Immunoblotting showed that JMJD8 was expressed at higher levels in lung cancer cells than in HBE (normal bronchial epithelial) cells." (PMID 33442397, 2021). "JMJD8 shows potential as a prognostic marker for lung cancer patients, providing a new target for therapeutic strategies." (PMID 33442397, 2021).
nasopharyngeal carcinoma (1 paper, 2016). A carcinoma arising from the nasopharyngeal epithelium. "The same effect was observed with JMJD8 knockdown in HONE1 (Nasopharyngeal carcinoma cells), HaCat (Immortalized human keratinocytes) and U2OS (Osteosarcoma cells) cell lines indicating that the observed defects in NF-κB activation caused by JMJD8 knockdown is not cell-type specific." (PMID 27671354, 2016).
neuroblastoma (1 paper, 2022). Neuroblastoma (NB) is the most common solid, extracranial childhood tumor. "In addition, T-cell dysfunction was found related to JMJD8 in neuroblastoma and BRCA via TIDE web tool and a negative correlation was discovered between CTL and JMJD8 in BRCA." (PMID 35898493, 2022).
non-small cell lung carcinoma (1 paper, 2021). A group of at least three distinct histological types of lung cancer, including non-small cell squamous cell carcinoma, adenocarcinoma, and large cell carcinoma. "The underlying biological functions and molecular mechanisms of JMJD8 in non-small-cell lung cancer (NSCLC) remain unclear." (PMID 33442397, 2021).
prostate carcinoma (1 paper, 2020). A carcinoma that arises from epithelial cells of the prostate gland. "Similarly, JMJD8 downregulation reduces the viability of DU145 prostate cancer cells." (PMID 33029143, 2020).
squamous cell carcinoma (1 paper, 2021). A carcinoma arising from squamous epithelial cells. "In poorly differentiated adenocarcinomas and squamous cell carcinomas, JMJD8 showed strong staining and weak staining, respectively, in the bronchial epithelium." (PMID 33442397, 2021). "Furthermore, the knockdown of JMJD8 strongly inhibited squamous cell carcinoma cell invasion 20 and affected DU145 cell viability." (PMID 33442397, 2021).
cancer (8 papers, 2017 to 2025). A tumor composed of atypical neoplastic, often pleomorphic cells that invade other tissues. "Surprisingly, we discovered that high JMJD8 was associated with a majority of RNA modulator genes in many cancers, including m1A, m5C, and m6A, indicating that JMJD8 was involved in RNA modifications." (PMID 35898493, 2022). "The extra exploration of the association between JMJD8 and other immunosuppressive cells in pan-cancer indicated that JMJD8 also functioned in CAFs, Tregs, and MDSCs and inhibited the anticancer immune by targeting CTLs." (PMID 35898493, 2022). "Focusing on M2 macrophages, we conducted multiple algorithms on TIMER2.0 to analyze the correlation between their infiltration level and JMJD8 expression in pan-cancer, and the association was observed in BLCA, HNSC, STAD, TGCT, UCEC, and UVM consistently presented." (PMID 35898493, 2022). "To seek whether JMJD8 can predict therapeutic responses to cancers, we obtained the data from ROCplotter to show the association between the therapeutic outcomes and JMJD8 expression in four cancer types (BRCA, OV, GBM, and CRC)." (PMID 35898493, 2022). "Interestingly, we identified CD276 with an exceptionally high association with JMJD8 in 15 cancer types." (PMID 35898493, 2022). "JMJD8 functions as a cancer-causing protein in some cancer cell lines, including endothelial cells." (PMID 31152315, 2019). "Also, Tregs were positively associated with JMJD8 in 13 cancers." (PMID 35898493, 2022). "However, JMJD8 was also positively associated with them in several cancers like UVM." (PMID 35898493, 2022). "In non-small cell lung cancer (NSCLC), JMJD8 enhances the proliferation and invasion of cancer cells by stabilizing the epidermal growth factor receptor (EGFR), thereby inhibiting the degradation of the overexpressed EGFR." (PMID 40761260, 2025). "JMJD8 was previously reported to affect DNA repair genes, but pan-cancer evidence is required for further exploration." (PMID 35898493, 2022). "JMJD8 has recently been identified as a cancer-related gene, but current studies provide limited information." (PMID 35898493, 2022). "The top 100 JMJD8 coexpressed genes in pan-cancer were analyzed on GEPIA2.0, and the top 5 genes (C16ORF58, IFT140, ITFG3, PIGQ, and WDR24) showed high correlations with JMJD8 in the majority of cancer types." (PMID 35898493, 2022). "The UALCAN results exhibited that JMJD8 protein was upregulated in cancers of BRCA, UCEC, and GBM and downregulated in LIHC and HNSC." (PMID 35898493, 2022). "Here, we comprehensively introduced a recently identified cancer gene, JMJD8; described its clinical significance, multi-omics characteristics, and roles in cancer immunity; and screened potential target drugs in pan-cancer." (PMID 35898493, 2022). "For no testing data of XMD-1150, XMD-892, genipin was found; we exhibited the GI50s of THM-I-94 and compared them with the JMJD8 expression in pan-cancer cell lines." (PMID 35898493, 2022). "To further investigate the JMJD8 in cancer immune, we analyzed its expression in levels of immunocytes." (PMID 35898493, 2022). "We also compared JMJD8 expression in the collected cancer single-cell datasets and discovered that M2 or undefined macrophages expressed it in BLCA, CHOL, GBM, HNSC, and LIHC." (PMID 35898493, 2022). "We used TIMER2.0 to display the correlations between JMJD8 and Tregs, CAFs, and MDSCs, JMJD8's positive correlations with at least two cell types were observed in several cancers, including CESC, COAD, HNSC, LUSC, PAAD, STAD, and THYM." (PMID 35898493, 2022). "We also searched TIDE for the interplays between JMJD8 promoter methylation and cancer subtypes, CTL, and risks." (PMID 35898493, 2022). "Here, we discovered that higher JMJD8 expression is correlated to low immune infiltration, immunosuppressive cancer subtypes, and globally reduced cytokine receptors." (PMID 35898493, 2022).
cancer (continued). "CD276 showed the highest positive correlations with JMJD8 in 15 cancers, followed by LGALS9, VSIR, and TNFRSF4." (PMID 35898493, 2022). "Pan-cancer bulk sequencing data and online web tools were applied to analyze JMJD8’s correlations with prognosis, genome instability, cancer stemness, DNA repair, and immune infiltration." (PMID 35898493, 2022). "The GEPIA2.0 results show that JMJD8 mRNA in cancers was highly expressed in DLBC, THYM, LGG, and PAAD but poorly expressed in TGCT and UCS." (PMID 35898493, 2022). "For cancer stemness, we noticed that JMJD8 obtained strong correlations with it in OV, followed by LGG, UVM, HNSC, and ESCA." (PMID 35898493, 2022). "From the bulk, spatial, single-cell transcriptional data and the fluorescence staining results above, we confirm the close association between JMJD8 and M2 macrophages, and these suggested that JMJD8 is a potential cancer-specific marker." (PMID 35898493, 2022). "The results from multiple perspectives demonstrated that JMJD8 is a critical factor in immunosuppressive environment construction in many cancers, probably via suppressing immunostimulator function and immune checkpoint effects." (PMID 35898493, 2022). "Conclusively, we performed multi-omics pan-cancer analyses of JMJD8 and identified it as a prognostic biomarker." (PMID 35898493, 2022). "Some findings suggest that JMJD8 plays a pro-cancer role, while others suggest that it plays an anti-cancer role." (PMID 36613903, 2022). "Their strong positive correlations in cancers suggest that high JMJD8 promoted the promoter methylation of its target genes and suppressed their expression." (PMID 35898493, 2022). "We also noticed that high JMJD8 promoter methylation was positively correlated with most immunostimulators, demonstrating that JMJD8 expression affected chemokine-mediated immunostimulations against cancers." (PMID 35898493, 2022). "JMJD8 was positively correlated with TMB in 2 cancers (LGG and UCEC) and with MSI in 7 cancers (COAD, KICH, KIRC, LIHC, LUSC, TGCT, and UCEC)." (PMID 35898493, 2022). "We then found that high JMJD8 correlated with high expression of mismatch repair genes, stemness, homologous repair gene signature in more than 9 cancers." (PMID 35898493, 2022). "As visualized in heatmaps, JMJD8 was negatively associated with several chemokines (CXCL9, 10, 11, 12, and 13), many receptors, and immunostimulators in pan-cancer." (PMID 35898493, 2022). "JMJD8 was highly associated with immune checkpoint CD276 and was an M2 macrophage biomarker in many cancers." (PMID 35898493, 2022). "For aneuploidy, JMJD8 was positively correlated with it in 3 cancers (ESCA, HNSC, and UVM) and negatively associated with 7 cancers (TGCT, UCEC, KICH, SARC, KIRC, KIPAN, and BRCA)." (PMID 35898493, 2022). "Since the DMPsi reflexed the DNA methylation status of cancer, we subsequently sought the JMJD8’s influences on cancer epigenetic modulations." (PMID 35898493, 2022). "This study will reveal JMJD8’s roles in pan-cancer and its potential as a novel therapeutic target." (PMID 35898493, 2022). "We confirmed it as a biomarker of M2 macrophage infiltration in various cancers and speculated that JMJD8 mediated the CSC immunity surveillance, M2 macrophage polarization, and CD8+ T-cell depression induced by CD276." (PMID 35898493, 2022). "JMJD8 may participate in DNA repair via MMR or HDR to promote cancer genome stability, stemness maintenance, and chemoresistance in cancer cells." (PMID 35898493, 2022). "The role of the novel identified gene JMJD8 in cancer progression remains controversial." (PMID 35898493, 2022). "Finally, we compared the JMJD8 expression differences between pre- and post-cytokine treatment in cancer cell lines on web tool TISMO." (PMID 35898493, 2022). "Subsequently, we explored whether JMJD8 was differentially expressed in diverse cancer immune subtypes via TISIDB." (PMID 35898493, 2022).